MIR4706 (microRNA 4706)
Synonyms: hsa-mir-4706; mir-4706
Gene: MicroRNA gene on chromosome 14 (65,044,688 to 65,044,769, forward strand). Ensembl gene ENSG00000266531.
Homologues: Orthologues: chimpanzee MIR4706 (100% identical).